CD70 (CD70 molecule)
Diseases named in the same sentence as CD70 in open-access papers (continued):
Sharing a sentence is not in itself a finding about the gene and the disease.
renal cell carcinoma (continued). "CD70 expression in renal cell carcinoma has already been described in several studies, although with varying positivity for CD70." (PMID 31652572, 2019). "The increases in CD70 protein levels in renal cell carcinoma cells they showed was likely more dependent on oxygen levels rather than the expression levels of HIFs, offering a possibility of the involvement of HIF-independent pathways." (PMID 29721188, 2018). "The cell surface receptor CD70 has been previously reported as a promising target for B-cell lymphomas and several solid cancers including renal cell carcinoma." (PMID 28915592, 2017). "Subsequently, CD70 has been found to be overexpressed in renal cell carcinoma (RCC), adenocarcinoma of pancreas and ovaries, breast and colon cancer, glioblastoma, laryngeal carcinoma and melanoma." (PMID 28915592, 2017). "In summary, the in vitro and in vivo preclinical data provided herein for CD70 expressing tumor cells of renal cell carcinoma origin supports the further development of a CD70-TTC for this indication." (PMID 28915592, 2017). "CD70+ renal cell carcinomas tumours typically also have homogeneous high-intensity staining (3–4+, data not shown)." (PMID 20664585, 2010). "We have previously shown targeting CD70 in renal cell carcinomas (clear cell and papillary types) and in haematologic malignancies (HL, MM) using anti-CD70-drug conjugates." (PMID 20664585, 2010). "While most research has focused on solid tumors such as renal cell carcinoma, the selective expression profile of CD70 in hematological malignancies suggests that CD70-directed radioligand therapies could be explored for leukemias and lymphomas." (PMID 40227793, 2025). "Furthermore, the expression of CD27, a member of the tumor necrosis factor receptor superfamily, has been associated with immune modulation in cancer, with its ligand CD70 being regulated by hypoxia-inducible factors in renal cell carcinoma." (PMID 40458414, 2025). "Notably, recent studies of allogeneic CAR-T cells targeting CD70 have demonstrated promising safety and efficacy signals in renal cell carcinoma (RCC) and T-cell non-Hodgkin lymphoma (T-NHL)." (PMID 40698082, 2025). "Interestingly, CD70 is frequently expressed on T- and B-cell lymphomas and a significant fraction of solid tumors, such as thymic carcinoma, glioblastoma, renal cell carcinoma, osteosarcoma, and nasopharyngeal carcinoma." (PMID 38637886, 2024). "In renal cell carcinoma, CD70 induction was reported under hypoxic conditions." (PMID 34991665, 2022). "For example, SGN-CD70A underwent phase I trial in CD70-positive renal cell carcinoma patients." (PMID 35145909, 2021). "The highest number of CD70 positive cells was detected in renal cell carcinoma." (PMID 31652572, 2019). "Interestingly, many of these studies are conducted against renal cell carcinomas where constitutive HIF-2α activation is frequently observed due to VHL mutations and CD70 is highly expressed." (PMID 29721188, 2018). "In addition to its function and transient expression limited to innate and adaptive immune cells, abundant CD70 expression has been documented in B cell malignancies and renal cell carcinoma." (PMID 25792975, 2015). "Indeed, such a CD70-mediated expansion of Tregs corroborates with the proposed role of CD70 in tumor immune escape in renal cell carcinoma." (PMID 23840967, 2013). "CD70 is a rapidly internalising cell surface antigen that shows a minimal expression on normal tissue but is frequently upregulated on haematologic malignancies, nasopharygeal carcinomas, and renal cell carcinomas." (PMID 20664585, 2010). "We have previously reported finding CD70 expression in about 70% of renal cell carcinoma cases." (PMID 20664585, 2010). "Renal cell carcinoma (RCC), a highly malignant tumor originating from the renal parenchyma and tubule epithelium, frequently overexpresses CD70 despite its role as a costimulatory immune molecule." (PMID 40896423, 2025).
renal cell carcinoma (continued). "Interestingly, one of the studies used CD70 KO anti-CD70 CAR Ts against renal cell carcinoma (RCC)." (PMID 41354926, 2025). "CD70 expression is normally restricted to a small subset of highly activated T-cells, B cells, and dendritic cells (DCs); however, CD70 has been found to be upregulated in large B-cell leukemia and lymphoma, T-cell leukemia, renal cell carcinoma, and glioblastoma." (PMID 35011583, 2021). "CD70 has emerged as a promising immunotherapeutic target in renal cell carcinoma (RCC), with both CD70-directed monoclonal antibodies and chimeric antigen receptor (CAR)-based therapies currently under development." (PMID 41533507, 2026). "CTX130, an anti-CD70 CAR-T therapy, is under development for T-cell lymphoma (NCT04502446) and renal cell carcinoma (RCC, NCT04438083), employing electroporation for ex vivo gene editing." (PMID 40801569, 2025). "The CD70/SIRPα bispecific antibody was able to target CD70-expressing cells including NHL and renal cell carcinoma and facilitate the engagement of macrophages." (PMID 33790906, 2021). "Due to the constitutive expression of CD70 on solid tumors and B-cell lymphomas, several CD70-targeting molecules including antibodies and ADCs have recently entered preclinical and clinical testing in NHL and renal cell cancer." (PMID 28915592, 2017). "The high percentage of renal cell carcinomas and NHL samples that express CD70 provides a strong rationale for clinical testing and a phase I clinical trial of SGN-75 in these patient populations is currently in progress." (PMID 20664585, 2010). "SGN-75, an auristatin-based anti-CD70 ADC, recently entered a phase I clinical trial for patients with renal cell carcinoma and NHL." (PMID 20664585, 2010). "And CD70 expression is also being detected in nonhematologic malignancies, for example, renal cell carcinoma and glioblastoma." (PMID 35978433, 2022). "CD70 is highly expressed on several malignancies including NHL and renal cell carcinoma (RCC)." (PMID 31500657, 2019). "In contrast to a total lack of constitutive CD70 expression in normal tissue, CD70 overexpression has been documented in diverse tumor types such as renal cell carcinoma, glioblastoma, and hematological malignancies." (PMID 25951351, 2015). "The specific binding of mAbs 1C1 and 5D12 to CD70 was analysed by western blot analysis using purified FLAG-tagged CD70 ECD and membrane-enriched samples from HEK 293F parental, CD70-transfected HEK 293F cells and a CD70+ renal cell carcinoma cell line (786-O)." (PMID 20664585, 2010). "CTX-130 (as an anti-CD70 CAR-T) has been tested in the COBALT-LYM (T-cell lymphoma) and COBALT-RCC (advanced clear cell renal cell carcinoma) studies." (PMID 40574859, 2025). "Unlike findings in renal cell carcinoma, we found a predominant interaction between CD27 and CD70 expressed by stromal cells compared to tumor cells, even when considering only the interaction with CD8+T cells expressing CD27." (PMID 40148586, 2025). "In comparison to CD70 mAb + SIRPα mAb treatment, CD70/SIRPα BsAb had a greater ability to phagocytose CD70-expressing NHL and renal cell carcinomas in vitro, but no apparent differences were observed in vivo." (PMID 35978372, 2022).
glioblastoma (34 papers, 2010 to 2026). The most malignant astrocytic tumor (WHO grade IV). "Prior studies have also shown that CD70 expression was linked to a poor prognosis with glioblastoma." (PMID 36146527, 2022). "Treatment with 32-134D also decreased the expression of CD70, which has been implicated in immune evasion of cancer cells through induction of T cell exhaustion or apoptosis in glioblastoma and RCC." (PMID 35499076, 2022). "Upon silencing of CD70 in glioblastoma cell lines, expression levels of EMT-associated genes, SOX2 and CD44, decreased, resulting in inhibition of tumor growth and migration." (PMID 34991665, 2022). "Previous studies showed that CD70-expressing cancer-associated fibroblasts showed increased migratory capacities, and inhibition of CD70 in primary glioblastoma suppressed tumor migration." (PMID 35216458, 2022). "Nonetheless, it is already known that in glioblastoma, CD70 expression has been implicated in escape from immune surveillance." (PMID 25951351, 2015). "CD70, is an antigen that is overexpressed in glioblastoma and is associated with poor survival." (PMID 41208963, 2025). "CD70, a member of the tumor necrosis factor receptor superfamily, is expressed in glioblastoma (GB), where it promotes tumor growth, migration, and immunosuppression." (PMID 41716471, 2026). "CXCR1- and CXCR2 modified CD70 engineered CAR T cells demonstrated increased intratumoral infiltration in glioblastoma in an in vivo model." (PMID 39835140, 2024). "CD70 is also highly expressed in renal cancer, glioblastoma, and ovarian cancer tissues, as demonstrated by analyses from the Cancer Genome Atlas (TCGA) database and immunohistochemical (IHC) staining results, along with findings from previous studies." (PMID 39906740, 2024). "In glioblastoma, preclinical investigations using CD70-specific CAR T cells have come up with promising findings, motivating researchers to move with this tumor antigen for possible clinical translations." (PMID 36721153, 2023). "A study validated the efficacy of anti-CD70 in glioblastoma, wherein anti-CD70 treatment contributed to the regression of glioblastoma." (PMID 35222533, 2022). "The ligand CD70 is frequently overexpressed in several solid cancers, most prominently renal cancer (87%) but also including lung cancer (10%), glioblastoma (42%), and ovarian cancer (15%)." (PMID 36180422, 2022). "Ablation of CD70 in glioblastoma cells reduced genes correlated with tumor epithelial mesenchymal transition (EMT), such as SOX-2 and CD44, and inhibited the migration and growth of the tumor." (PMID 32429463, 2020). "The importance of determining an effective dose was also demonstrated by a study on TanCAR targeting CD70 and B7-H3, both of which are expressed in glioblastoma and have been studied individually, where there was incomplete eradication and, ultimately, antigen loss." (PMID 37754534, 2023). "CD70 was discovered to be a new immunosuppressive ligand in wild-type LGGs and glioblastoma." (PMID 36146527, 2022). "A recent study reported an association between CD70 expression and infiltration of CD163+ (a marker of M2 macrophages) tumor-associated macrophages (TAMs) in glioblastoma, suggesting a (in)direct role for CD70 in recruitment and/or activation of tumor promoting TAMs." (PMID 34991665, 2022). "This also indicates that CD70 could be used to increase positive outcomes, not only in primary glioblastoma patients but also in recurrent GBM that were found to be very highly expressing CD70." (PMID 32429463, 2020). "In addition, radiation enhanced CD70 expression on glioblastoma cells, offering good prospects to improve the antitumor efficiency to integrate standard care with CD70 CAR T-cell therapy." (PMID 32429463, 2020). "CD70 has been reported to be highly expressed in renal cell (clear and papillary types), thymic, nasopharyngeal, and brain (astrocytoma, glioblastoma) tumours." (PMID 20664585, 2010).
glioblastoma (continued). "In glioblastoma multiforme (GBM), CD70 plays a key role in recurrent GBM cell aggressiveness and maintenance." (PMID 40205178, 2025). "The use of CAR-T cells in glioblastoma is based on targeting the tumor-specific or tumor-enriched antigens like IL-13Rα2, EGFR/EGFRvIII, HER2, CD70, B7-H3, and CD133/CD44." (PMID 41208963, 2025). "CD70 overexpression independently predicts poor survival in low-grade glioma (LGG) and glioblastoma (GBM) multiforme and promotes macrophage infiltration and CD8+ T-cell apoptosis, making it a compelling CAR-T target." (PMID 40896423, 2025). "CXCR1 and CXCR2-modified CD70-specific CAR T cells have been demonstrated to improve T cell trafficking and antitumor efficacy via IL-8-mediated chemotaxis in an in vivo glioblastoma model." (PMID 36721153, 2023). "Other antigens tested in glioblastoma models, most of which have already made it into clinical testing as below, include EphA2, B7-H3, CD133, CD70, GD2, NKG2D, Fn14, and podoplanin." (PMID 37754534, 2023). "Human and mouse CD70-specific CAR T cells were able to recognize and eliminate CD70-positive glioblastoma tumors in vitro, as well as in xenograft and syngeneic models, without imparting significant toxicity." (PMID 36721153, 2023). "NCT05353530 is phase I trial designed to test CD70-directed CAR-Ts applied intravenously after the end of radiotherapy in patients with newly diagnosed CD70-positive and MGMT-unmethylated glioblastoma, IDH wildtype." (PMID 35885047, 2022). "Here, they also showed that the presence of CD70 on tumor cells and CD163 on TAMs correlated with poor prognosis for glioblastoma patients." (PMID 34991665, 2022). "Recently, the putative markers frequently being used to identify and/or isolate glioblastoma stem cells (GSCs) include: CD133, CD44, CD15, CD70 (CD27 L), S100A4, ALDH1A3, Nanog, OCT-4, SOX-2, and Nestin." (PMID 32429463, 2020). "CD70-directed CAR-T has shown efficacy in acute myeloid leukemia, renal cancer, and glioblastoma." (PMID 40896423, 2025). "This information on IL-8 and CD70, let to the generation of CD70-targeting CAR with a modified IL-8 receptor (called 8R-70CAR) that let to complete tumor regression of advance cancers in pre-clinical studies, including glioblastoma." (PMID 41208963, 2025). "The glioblastoma antigens currently targeted in the clinic, often in combination, are Cluster of Differentiation proteins (CD133, CD44 & CD70), IL receptors (IL-13Ra2), EGFR and EGFRvIII, ephrin receptor A2 (EphA2), human epidermal growth factor receptor 2 (HER2) and B7-H3." (PMID 41208963, 2025). "However, recent studies reported overexpression of CD70 on multiple tumor cells, like solid cancers, for example, renal cell cancer (RCC), glioblastoma, and hematological malignancies." (PMID 35978433, 2022). "Human brain tumor cells, such as malignant glioma like or glioblastoma multiforme, express CD70, and this CD70 – but not TNFα or FasL – initiated T-cell death through the receptor-dependent pathway." (PMID 23692980, 2013).
lymphoma (32 papers, 2006 to 2025). A malignant (clonal) proliferation of B- lymphocytes or T- lymphocytes which involves the lymph nodes, bone marrow and/or extranodal sites. "This is highlighted in patients with CD70 mutation who have an increased susceptibility to EBV-associated lymphomas." (PMID 35264785, 2022). "Our clinical data, scRNA‐seq analysis and murine lymphoma model clearly showed that high CD70 expression might be associated with an increased number of exhausted T cells and thus a more immunosuppressive TME." (PMID 36471481, 2022). "In preclinical studies, CAR-NK cells targeting CD30 or CD70 demonstrated significant anti-lymphoma activity." (PMID 40806636, 2025). "We further tested the blockade of CD70 in combination with PD‐L1 inhibitor in a murine lymphoma model." (PMID 36471481, 2022). "Latent EBV infection has been shown to induce the expression of CD70 on host cells, including lymphoma cells." (PMID 36471481, 2022). "In this study, CD70-positive biopsy-derived primary lymphoma B cells more potently enhanced Foxp3 levels in CD4-positive CD25−negative T cells subpopulation than their CD70-negative counterparts." (PMID 35681499, 2022). "On the other hand, the constitutive expression of CD70 observed in chronic viral infection and lymphoma leads to immune exhaustion." (PMID 35145909, 2021). "In a retrospective study, nearly half (11/21) of CD70-deficient and 36% (12/33) of CD27-deficient patients developed lymphomas, with Hodgkin’s lymphoma (HL) being the most common malignancy." (PMID 34638238, 2021). "Lymphoma cells can also recruit and “reeducate” surrounding cells to their advantage, for example, by modulating CD70 expression levels." (PMID 30874354, 2019). "Nevertheless, we were able to identify solid tumours and lymphomas with different CD70 expression levels and we believe that our unified method can improve the stratification of patients for immunotherapy." (PMID 31652572, 2019). "Therefore, blocking the CD70/CD27 signaling axis represents a novel approach in lymphoma immunotherapy." (PMID 40078987, 2025). "Lymphoma-bearing mice were used to validate in vivo potency of CD70-CAR NK cells." (PMID 38331849, 2024). "The interaction between CD70 and CD27 can stimulate the proliferation and survival of cancer cells and increase the level of soluble CD27, which is associated with poor prognosis in patients with lymphoma and certain solid tumors." (PMID 37849799, 2023). "Thus, it is a promising therapeutic target for the treatment of many major CD70+ cancer indications, including CD70+ lymphoma, RCC, NSCLC, HNSCC and OC." (PMID 37849799, 2023). "We next tested the hypothesis that coinhibition of CD70 and PD‐L1 could rescue exhausted T cells and effectively reduce lymphoma growth in vivo." (PMID 36471481, 2022). "A broad range of tumors, including 50–60% of lymphomas, overexpress CD70." (PMID 36654819, 2022). "Furthermore, CD70+ lymphoma B cells have been shown to partially contribute to Foxp3 expression in intratumoural CD4+CD25− T cells and thus the associated regulatory activity." (PMID 36471481, 2022). "Constitutive CD27 and CD70 expression has also been detected on T cell neoplasia such as anaplastic large cell lymphoma, peripheral T cell lymphoma, cutaneous T cell lymphoma, adult T cell leukemia/lymphoma and extranodal NK/T cell lymphoma." (PMID 34991665, 2022). "In addition, modulation of both anti- and pro-apoptotic proteins, including the Bcl-2 family, has been described to be dependent of the presence of CD70/CD27 on malignant lymphoma cells." (PMID 34991665, 2022). "CD70 was upregulated in extrafollicular FL SCs, which suggests that CD70 may facilitate the infiltration of lymphoma cells into extrafollicular regions during tumour progression." (PMID 35332263, 2022). "Additionally, CD70-targeted CAR T cells elicited significant antitumor activity in a murine xenograft model of lymphoma." (PMID 35011583, 2021).